BAP1 (BRCA1 associated deubiquitinase 1)
Diseases named in the same sentence as BAP1 in open-access papers (continued):
Sharing a sentence is not in itself a finding about the gene and the disease.
tumor (continued). "Similarly, BAP1-negative tumours (n = 30) had a higher expression of HIF1a (p < 0.001) and a lower expression of VHL (p = 0.003) compared to BAP1-positive tumours (n = 24)." (PMID 31323773, 2019). "For VHL wild-type tumors, other therapy modalities aiming at pVHL non-related pathways controlled by tumor suppressors such as PBRM1, SETD2 or BAP1 may be more appropriate than the common anti-angiogenic treatment." (PMID 27530247, 2016). "Although MM tumor tissues were not available for MARF2-IV-2 and MARF40-III-1, IHC of MARF2-IV-2 giant bone tumor tissue indicated lack of BAP1 nuclear staining, supporting presence of LOH, as our previous studies have shown a 100% correlation between LOH and lack of nuclear staining." (PMID 26683624, 2015). "Consistently, depletion of BAP1 in MYCN-amplified BE2C and SH-EP Tet21/N cells but not MYCN non-amplified SH-EP Tet21/N+Dox cells, inhibited cell proliferation and migration in vitro and retarded tumor growth in subcutaneous and orthotopic xenograft mice models in a MYCN-dependent manner." (PMID 37543638, 2023). "Rather, it is plausible, given that BAP1 wild-type tumors appear to be more sensitive to combined HDAC and PD-1 inhibition in this trial, that the immune modulatory functions of HDAC inhibitors rather than their direct tumor cell-killing effect may be dominant." (PMID 34453044, 2021).
cancer (486 papers, 2008 to 2026). A tumor composed of atypical neoplastic, often pleomorphic cells that invade other tissues. "The efficacy of Tazemetostat was also evaluated in BRCA‐1 associated protein 1 (BAP1) inactivated cancers as preclinical data suggest that BAP1 inactivation leads to enhanced EZH2 expression associated with pronounced sensitivity to EZH2 inibition." (PMID 40181550, 2026). "Early detection of BAP1-TPDS is crucial as it enables the implementation of targeted cancer surveillance for at-risk individuals." (PMID 41551629, 2026). "The BAP1 cancer syndrome shows that individuals with inherited BAP1 mutations often develop multiple cancers with high penetrance." (PMID 40000790, 2025). "In our series, two patients with GU malignancies had confirmed germline BAP1 mutations, and half had strong family histories of cancer." (PMID 41409117, 2025). "Germline mutations of the deubiquitinase BRCA1-associated protein 1 (BAP1) lead to the “BAP1 cancer syndrome” characterized by development of cancers." (PMID 39984455, 2025). "The loss of BAP1 expression also impacts inflammatory pathways and immune evasion, further facilitating cancer progression." (PMID 40016284, 2025). "De novo missense variants in BAP1 are associated with neurodevelopmental Kury–Isidor syndrome, with assumed cancer predisposition similar to BAP1‐TPDS." (PMID 39344744, 2025). "BAP1, a deubiquitinase with a ubiquitin C-terminal hydrolase domain, plays diverse biological roles and has been linked to human cancer through advanced sequencing studies." (PMID 40000790, 2025). "Although hereditary UM is rare, germline BAP1 loss predisposes patients to UM and various other cancers." (PMID 40283643, 2025). "Despite these insights, the specific role of loss of BAP1 function in the development of different cancers and their metastases is unclear." (PMID 41022584, 2025). "Brca1-associated protein 1 (BAP1) is an H2A deubiquitinase that induces ferroptosis of cancer cells by inhibiting SLC7A11." (PMID 40689204, 2025). "Carriers of germline BAP1 mutations often suffer multiple cancers during their lifetime, a condition was named the “BAP1 cancer syndrome”." (PMID 40083694, 2025). "Significance: Deadly cancers with BAP1 mutations suppress autophagy by phosphorylating the autophagy regulator BECN1 via the proto-oncogene SRC." (PMID 40754831, 2025). "BAP1 showed high propensity for biallelic loss in cervical (100%), biliary tract (88.9%), ovarian (80.0%), kidney (76.5%) cancers." (PMID 40420266, 2025). "BAP1 loss disrupts these processes, making cells more vulnerable to DNA damage and other cancer-promoting factors." (PMID 40362535, 2025). "It has been reported that individuals with multiple BIMTs or a personal history of BAP1-related cancers have a 70% chance of having a pathogenic variant of BAP1." (PMID 40649916, 2025). "Pathogenic variants in BAP1 confer a high risk of various cancers, including UM (16-36% risk), with a median onset age of 53 years compared to 62 years for sporadic forms." (PMID 39926282, 2025). "Our data showed that nuclear BAP1 expression is the most associated with cancer clinical outcomes and other biomarkers." (PMID 40136571, 2025). "Mutations in the BAP1 gene lead to several aggressive cancers, including RCC, malignant mesothelioma, uveal melanoma, and cutaneous melanoma." (PMID 40688406, 2025). "The ’BAP1 Malignant Syndrome’ was recently defined, and it demonstrates a significant correlation between germline mutations and cancer susceptibility, particularly melanoma, uveal cancer, PM, and renal carcinoma." (PMID 40506895, 2025). "BAP1 families require genetic and oncological counseling to handle cancer risk management and undergo routine testing for at-risk family members." (PMID 40361508, 2025).
cancer (continued). "To evaluate the potential of these compounds as a treatment for BAP1-deficient cancers, we initially implanted UMRC-6 cells subcutaneously in mice." (PMID 40754831, 2025). "Cancer prognosis can be determined based on the mutation status of additional genes like BRCA1-associated protein-1 (BAP1), Splicing Factor 3B Subunit 1 (SF3B1), and eukaryotic translation initiation factor 1A x-linked (EIF1AX)." (PMID 40283643, 2025). "Further, we found that the 15-GEP SVM discriminant score is a better indicator of tumors in transition from Class 1 to Class 2 than is the fraction of cancer cells harboring a BAP1 mutation (CCFBAP1)." (PMID 41387680, 2025). "Approximately 1 to 2% of UM and 22% of familial cases have been linked to hereditary cancer predisposition and result from pathogenic genetic variations, primarily in the BAP1 gene, and more recently in MBD4." (PMID 39926282, 2025). "Our data strongly suggest exploring these drug combinations in clinical trials for cancer patients with BAP1 loss, particularly those with metastatic UM, for whom current treatment options are very limited." (PMID 40754831, 2025). "Similar to human BAP1 mutation carriers, heterozygous Bap1-mutant mice develop a spectrum of spontaneous malignant tumors, including rare MMs." (PMID 38592450, 2024). "Beyond cancer, we also examined the association between UK Biobank BAP1 variants and quantitative traits." (PMID 38969833, 2024). "The BAP1 gene, located on chromosome 3, harbors loss-of-function mutations associated with various cancers, including UM (found in poor-prognostic subgroups Classes 3/C or 4/D)." (PMID 38920653, 2024). "This overlap included a higher frequency of BAP1 somatic cancer driver mutations, striking intratumorally adaptive immune responses, and enrichment for gene expression related to the EMT pathway." (PMID 39592856, 2024). "For many cancer types, the loss is arm level, spanning large regions of the ∼90 Mb chromosome 3p arm on which BAP1 is located and including regions corresponding to over 1000 annotated genes." (PMID 39554490, 2024). "On the other hand, the association with BAP1 somatic cancer driver mutations (P = 0.019) and IL20RB expression (P = 0.223) appeared to be ccRCC specific (Dataset EV5)." (PMID 39592856, 2024). "BAP1 status in PM histologic examination can inform diagnosis, prognosis, and possibily cancer prevention in those patients with hereditary BAP1 mutations, and it is a main focus of clinical research for personalized treatments." (PMID 38673021, 2024). "To understand the specific impact of BAP1 loss in both cancer and normal biology, we developed an RNA expression-based BAP1 activity score and validated this score in external human and mouse liver datasets." (PMID 39554490, 2024). "Although BAP1 mutations have been studied in a small subset of cancer types, there has been limited incorporation of other types of alterations that can lead to BAP1 loss." (PMID 39554490, 2024). "We developed an expression-based BAP1 activity score and identified a transcriptional profile associated with BAP1 disruption in cancer." (PMID 38045292, 2024). "In particular, there is overwhelming evidence that germline mutations in BAP1 predispose carriers to MM and certain other benign and malignant tumors." (PMID 38592450, 2024). "Copy number loss of BAP1 is found in ∼20% of TCGA pan-cancer samples, making it the most common alteration of BAP1 in this cohort." (PMID 39554490, 2024). "We identified 37 individuals with likely pathogenic or pathogenic variants in BAP1 from 35 families; most individuals (81.1%) had a history of cancer." (PMID 38824259, 2024). "Our results from the TCGA cancer dataset suggest that loss of BAP1 leads to dysregulation of mechanisms governing cell fate and consequently to changes in cell states." (PMID 39554490, 2024).
cancer (continued). "Since cancer alterations in BAP1 are typically caused by genetic mutations leading to protein loss of function, we have also generated deletion alleles of its ubh-4 C. elegans ortholog." (PMID 36980270, 2023). "BAP1 is frequently inactivated in MPM, and germline BAP1 mutation predisposes to some cancers, including MPM." (PMID 37445845, 2023). "Unbiased data are required to model the cancer risk of individuals who are heterozygous for a pathogenic BAP1 allele." (PMID 35920959, 2023). "For this purpose, the researcher obtains a pseudonymized data set from Hospital X consisting of WSIs and the associated diagnosis, information about other cancers, patient outcome, and BAP1 mutation status." (PMID 37142591, 2023). "These variants have been associated with diverse types of cancer and both produce structural destabilization of BAP1." (PMID 36980270, 2023). "In vitro BAP1 PARylation combined with MS enabled the identification of multiple sites that were PARylated, and many of these sites were mutated in various human cancers." (PMID 37009801, 2023). "SLC7A11, as a main BAP1 target gene in ferroptosis of cancers cell, is regulated by BRCA1-associated protein 1 (BAP1) on epigenetic mechanism." (PMID 37250891, 2023). "These BAP1 cancer-related missense mutations were p.F81V and p.A95D, which correspond to C. elegans p.F73V and p.A87D, respectively." (PMID 36980270, 2023). "Recently, the tumor suppressor gene breast cancer type 1 BRCA1-associated protein 1 (BAP1) was shown to antagonize HDAC4 activity to reduce proliferation." (PMID 36762207, 2023). "SLC7A11 is upregulated by BRCA1-associated protein 1 (BAP1) inactivation in cancer cells, which increases the uptake of cystine and the synthesis of GSH to develop the growth of cancer by inhibiting ferroptosis." (PMID 37458878, 2023). "Germline mutations of BAP1 demonstrated a better prognosis in some cancer types but somatic mutations caused a worse prognosis in other cancer types." (PMID 37543638, 2023). "This RNAi sublibrary included clones that inactivate proteasome subunits, proteasome-related enzymes, orthologs of known and putative BAP1 interactors, genes frequently mutated in cancer, and malignant BAP1-TPDS-related genes." (PMID 36980270, 2023). "Beyond this dysregulation, a variety of functionally similar genes associated with cancer progression were identified as upregulated in BAP1 KO MeT‐5A cells." (PMID 36740402, 2023). "BAP1 cancer syndrome highlights that all carriers of inherited BAP1-inactivating mutations develop at least one and often multiple cancers with high penetrance during their lifetime." (PMID 37009801, 2023). "Germline mutations of BAP1 exhibit a favorable prognosis in some cancer types but somatic mutations are related with worse prognosis in other cancer types." (PMID 37543638, 2023). "As for many rare cancer predisposition syndromes, there is limited scientific evidence to support the utility of surveillance and, therefore, management recommendations for BAP1 carriers are based on expert opinion." (PMID 37607989, 2023). "Genome editing with rAAV was used to first introduce a cancer-predisposition mutation on one BAP1 allele, generating MeT5A-BAP1w-/+ cells." (PMID 36669126, 2023). "BAP1 is a tumor suppressor gene whose alterations in cancer are commonly caused by gene mutations leading to protein loss of function." (PMID 36980270, 2023). "Previously, a Ca2+-regulated decrease in apoptosis has been implicated in the cellular transformation in BAP1-related cancers." (PMID 37479714, 2023).
cancer (continued). "Despite this data have undoubtedly pointed out a role for BAP1 in tumorigenesis of a specific spectrum of cancer, the determination of the molecular underlying mechanisms has not yet led to development of therapeutic strategies." (PMID 36318367, 2022). "Germline mutations in BAP1 can lead to a variety of cancers, and loss of BAP1 has also been proposed to induce aerobic glycolysis (the Warburg effect) in such carriers." (PMID 36077643, 2022). "It has also to be mentioned how the loss of BAP1 protein expression in several cancers can be observed in wild-type genes." (PMID 35204459, 2022). "Loss of BAP1 is implicated in a distinct subset of cancers that also include mesothelioma, clear cell renal cell carcinoma, and cholangiocarcinoma." (PMID 36077643, 2022). "We analyzed the presence of SNVs using a pan-cancer predisposition panel and identified UM mutations in BAP1 and GNAQ in 3/4 (75%) post-radiation AH samples (UM_005, 007, 012, and 013)." (PMID 35682905, 2022). "Intriguingly, BAP1 functions display also a high degree of tissue dependency, associated to a peculiar cancer spectrum and cell types of specific functions." (PMID 36318367, 2022). "Dysfunction of the BAP1 complex induced by the misregulation/mutations in its subunit(s) are frequent in many human cancers." (PMID 36180891, 2022). "Therapeutic approaches have been suggested for the treatment of BAP1-deficient cancers such as the epigenetic drugs that inhibit EZH2, ther platinum-based compounds and PARP-1 inhibitors." (PMID 36318367, 2022). "Other risk factors for this cancer include fair skin, light eye color, inability to tan, ocular or oculodermal melanocytosis, iris/choroidal nevus and BRCA1-associated protein 1 (BAP1) mutations." (PMID 36760885, 2022). "In pancreas, BAP1 inactivation causes organ atrophy while triggers the inactivation of tumour suppressor Hippo pathways in pancreatic KRAS mutated cancer." (PMID 36318367, 2022). "Analysis of other cancer risk genes yielded a secondary finding —BAP1:c.898_899delAG p.(Arg300Glyfs*6) likely pathogenic variant (class 4) in heterozygous form." (PMID 35381901, 2022). "BAP1 families require genetic and oncological counselling to handle cancer risk management and undergo routine testing for at-risk family members." (PMID 36318367, 2022). "Cancer-associated BAP1 mutations that inhibit the interaction between ASXL1/2 and BAP1 and impair DUB activity result in deregulated cell proliferation." (PMID 36068610, 2022). "BAP1 mutations were associated with worse cancer-specific survival (CSS) in both cohorts of the Memorial Sloan-Kettering Cancer Center (p = 0.002; HR 7.71; 95% confidence interval (CI) 2.08–28.6) and TCGA (p = 0.002; HR 2.21; 95% CI 1.35–3.63)." (PMID 35055428, 2022). "The germline mono-allelic mutation of BAP1 appears to play a role predisposition to exposure-induced cancers." (PMID 36318367, 2022). "Given the relatively young age at which these fatal cancers were diagnosed, it is plausible that one or both of these deceased family members carried an undiagnosed germline BAP1 mutation." (PMID 34504799, 2021). "Monosomy 3 (including loss of BAP1 copy number, or loss-of-function mutations in BAP1 gene) causes multiple cancer phenotypes including UVM." (PMID 34436011, 2021). "We have recently reported that loss of BAP1 function is a predictive biomarker for rTRAIL sensitivity in cancer." (PMID 34597666, 2021). "Different types of mutations, especially missense and truncating mutations, were observed in most of the subunits within the BAP1 complex across different cancer types." (PMID 33483476, 2021). "The most common inherited cancer risk factor associated with MPM is the aberration of BRCA1 Associated Protein 1 (BAP1), a deubiquitinating enzyme located on chromosome 3p21.1 acting as tumor suppressor gene." (PMID 34249695, 2021).